E2F1 (E2F transcription factor 1)
Diseases named in the same sentence as E2F1 in open-access papers (continued):
Sharing a sentence is not in itself a finding about the gene and the disease.
prostate carcinoma (continued). "A further analysis of E2F1 in prostate cancer showed that E2F1 was highly amplified in selective prostate cancer studies." (PMID 32354165, 2020). "The increased expression of E2F1 has been known to occur in many types of cancers, including prostate cancer." (PMID 32354165, 2020). "HES6 also drives a critical AR transcriptional program to induce castration-resistant prostate cancer through the activation of an E2F1-mediated cell cycle network." (PMID 33681178, 2020). "Knockdown of E2F1 in prostate cancer cell line DU145 results in the reduced expression of cytokines including Il-6." (PMID 33291686, 2020). "Loss of Rb during cancer progression correlated with increased levels of “free” E2F1 and androgen receptor (AR) levels in patients with castrate-resistant prostate cancer metastases." (PMID 30279956, 2018). "The development of castrate resistant prostate cancer involves activation of an E2F1 mediated cell cycle network, implicating E2F1 as a key player in the process." (PMID 30279956, 2018). "We previously found that NUSAP1 is overexpressed in recurrent prostate cancer and is regulated, at least in part, by loss of RB1 via the RB1/E2F1 axis." (PMID 28404898, 2017). "NUSAP1 expression is regulated by E2F transcription factor 1 (E2F1) and by loss of retinoblastoma-associated protein 1 (RB1), an important molecular pathway that becomes altered in aggressive forms of prostate cancer." (PMID 28404898, 2017). "Studies have suggested that E2F1 is the target gene of miR-20a, miR-106b, and miR-330 in prostate cancer." (PMID 26935418, 2016). "In a prostate cancer cell line, miR-20a directly inhibits the translation of the E2F1, E2F2 and E2F3 mRNA, and the endogenous E2F1, E2F2 and E2F3 bind to the promoter of the miR-17~92 cluster and activate its transcription." (PMID 27282946, 2016). "Bladder cancer and prostate cancer cells are chosen for this study based on the oncogenic role of E2F1 reported in these 2 malignancies." (PMID 25816777, 2015). "It has previously been demonstrated in prostate cancer that miR-330 acts as a tumour suppressor by downregulating E2F1 protein expression and the cellular levels of p-Akt, thereby promoting apoptosis of cancer cells." (PMID 26221725, 2015). "High E2F1 expression is associated with high levels of GLUT1 and PDK1 in these bladder and prostate cancer datasets." (PMID 25816777, 2015). "In prostate cancer miR-330-3p acts as a tumour suppressor by repressing the translation of E2F1 and Sp1." (PMID 26221725, 2015). "To test the role of E2F1 in regulating glycolysis, we over-expressed E2F1 or its DNA binding deficient mutant E2F1 (E138) in PC3 prostate cancer and UMUC3 bladder cancer cells." (PMID 25816777, 2015). "In prostate cancer biopsy specimens and in vitro culture, miR-330-3p expression was inversely correlated with expression of the E2F1 protein." (PMID 26221725, 2015). "E2f-1 is able to bind with the promoter of the insulin-like growth factor-I receptor (IGF-IR) gene in prostate cancer cells to promote the transcription of IGF-IR, thus enhancing the proliferation of tumor cells." (PMID 24393368, 2014). "Targeted knockdown by interferon RNA was applied on two prostate cancer and Hela cell lines to examine the inverse correlation expression of E2F1 and ICAM-1." (PMID 24742333, 2014). "E2F1 induces tumor cell survival via nuclear factor-kappa B (NF-κB) dependent induction of EGR1 transcription in prostate cancer cells." (PMID 24742333, 2014). "MiR-330 is reported to induce apoptosis in prostate cancer cells through E2F1-mediated suppression of Akt phosphorylation, and in our subnetwork NGFR (also known as P75NTR) is the target of miR-330." (PMID 21931774, 2011). "E2F1 immunostaining has been found to be prognostic in breast and lung cancers, and we now extendthis to prostate cancer." (PMID 21629784, 2011).
prostate carcinoma (continued). "MiR-330 induces apoptosis in prostate cancer cells through E2F1-mediated suppression of Akt phosphorylation, which strongly supports the coordinate gene regulation by this motif module and miR-330." (PMID 20946653, 2010). "When co-transfected with E2F1 expression vector, δ-catenin-luciferase activities were dramatically increased in prostate cancer cell lines." (PMID 21106062, 2010). "Recently, Pax6 and E2F1 were identified as positive transcriptional regulators for δ-catenin in the central nervous system and in prostate cancer cells." (PMID 21106062, 2010). "It was reported that E2F1 positively regulates the expression of δ-catenin in human prostate cancer cells, and the expression of both genes is altered in prostate cancer." (PMID 21106062, 2010). "Among them, E2F1 has been identified as a positive regulator of δ-catenin expression in prostate cancer cells." (PMID 21106062, 2010). "In this study, we demonstrated that Hes1 is a transcriptional repressor for δ-catenin and regulates δ-catenin expression in human prostate cancer cells and mouse models of prostate tumors by coordinating with transcription activator E2F1." (PMID 21106062, 2010). "Recently, we showed that the ectopic overexpression of E2F1 and Pax6 positively upregulates δ-catenin expression in prostate cancer cells." (PMID 19284555, 2009). "In our previous study, we identified E2F1 K117 as a novel SETD6 substrate in prostate cancer cells." (PMID 41540805, 2026). "For this reason, we performed apoptosis and cell proliferation assays showing that SETD6 KO in prostate cancer cells reduced apoptosis and induced cell proliferation that could be partially connected to K117 methylation of E2F1." (PMID 41540805, 2026). "Here, we explored how SETD6 methylation influences the E2F1 activity in prostate cancer cells." (PMID 41540805, 2026). "Based on these data, we were interested to find out whether methylation of E2F1 K117 by SETD6 has a more general role in the regulation of gene expression programs in prostate cancer cells." (PMID 41540805, 2026). "E2F1 is a transcription factor with important roles in the regulation of oncogenic signalling pathways, including cell cycle progression, apoptosis, and DNA repair, which influences cancer-related phenotypes in various malignancies including prostate cancer." (PMID 41540805, 2026). "E2F1 is a transcription factor with important roles in prostate cancer." (PMID 41540805, 2026). "In addition, orthogonal validation by Western blot analysis demonstrated that E2F1 protein expression was reduced in response to NXP800 treatment across all prostate cancer cells studied." (PMID 39787247, 2025). "This peptide, when conjugated with penetratin (PEP), elicited cellular uptake and has been demonstrated to bind to the E2F1 promoter to abrogate its transcription and downregulated E2F-responsive enzymes, leading to notable cytotoxicities in cell lines of lung cancer and prostate cancer." (PMID 39119602, 2024). "Furthermore, a study in prostate cancer demonstrated that upon exposure to doxorubicin E2F1 was recruited to the promoter region of ATM and repressed its expression." (PMID 38519707, 2024). "Through the analysis of the GRASSO prostate cancer database, we found that the expression of RACGAP1 was significantly increased in patients with PTEN, RB1, and E2F1 gene mutations, suggesting that E2F1 was related to RACGAP1." (PMID 37196108, 2023). "Notably, a remarkable decrease in E2F1 levels was observed upon MALAT1 depletion in prostate cancer cells." (PMID 37812088, 2023). "We also found that the expression of E2F1 promoted the progression of prostate cancer." (PMID 37196108, 2023). "E2F1 might regulate NUSAP1 expression in recurrent prostate cancer through binding CCAAT box in promoter region of NUSAP1." (PMID 36982952, 2023).
prostate carcinoma (continued). "In prostate cancer cells, Mdm2 competes with E3 ubiquitin ligase SCFSkp2 to bind to E2F1 and inhibits the ubiquitination of E2F1, thereby up-regulating the protein level of E2F1." (PMID 36770809, 2023). "E2F1 is known to play a key role in lineage plasticity during prostate cancer progression." (PMID 37440313, 2023). "Importantly, a recent report demonstrated that the E2F1-dependent induction of SREBP1 plays an important role in supporting the increased demand for lipid synthesis in prostate cancer cells." (PMID 36091143, 2022). "The results revealed that E2F1 (p = 0.0578), E2F6 (p = 0.0551), Gleason score (p = 0.0201), and tumor stage (p = 0.0065) were correlated with the disease-free survival of prostate cancer, though the p values of E2F1 and E2F6 were slightly below the cut-off for significance." (PMID 35531101, 2022). "Here we aimed to define the impact of E2F1/E2F2 deregulation in prostate cancer." (PMID 36230876, 2022). "We assessed the role of E2F in the sustained upregulation of nucleotide synthesis genes upon 5-FU exposure by transfecting PC3 and DU145 prostate cancer cells with two different sets of siRNA oligos specific for E2F1 and E2F2, and 24 h later treated the cells with 5-FU or vehicle for 72 h." (PMID 36230876, 2022). "Moreover, treatment of prostate cancer cells with E2Fi recapitulated the results obtained after siRNA knockdown of E2F1/E2F2 in combination with 5-FU treatment." (PMID 36230876, 2022). "In prostate cancer, it has been proposed that elevated E2F1 expression might contribute to the progression of hormone-independent PCa through its ability to repress the expression of the androgen receptor." (PMID 36230876, 2022). "Given the abnormal lipid accumulation in prostate cancer tissue and the unique function of avasimibe, we speculate that avasimibe exerts its anti-cancer effect by regulating E2F-1." (PMID 34461908, 2021). "A previous study in prostate cancer showed that P21 inhibits cell growth by targeting E2F1." (PMID 31998417, 2020). "Conclusion and significance: This proof-of-principle study demonstrates that targeting the E2F1/AR3 feedforward loop via a combination therapy or a multi-targeting drug could circumvent castration resistance in prostate cancer." (PMID 32354165, 2020). "SMYD3 is also highly expressed in prostate cancer, E2F-1 could exert its IGF-1R transactivation effect through both direct and indirect pathways." (PMID 32007952, 2020). "To assess whether E2F1 is critical in the progression of prostate cancer, we analyzed publicly available clinical databases by cancer type using cBioPortal." (PMID 32354165, 2020). "We inferred that TROAP might interact with c-Myc, E2F1, and TWIST in prostate cancer cells, but the association among the four genes was unclear." (PMID 33692939, 2020). "It has reported that E2F1 could promote invasion and migration of prostate cancer and osteosarcoma cells through regulating CD147 and DDR1 expression." (PMID 31801947, 2019). "KDM4A recruits E2F1 to control cancer metabolism for proficient prostate cancer growth." (PMID 30683841, 2019). "In addition, GAS5 interacts with E2F1 and enhances the binding of E2F1 to the P27Kip1 promoter in prostate cancer." (PMID 30853980, 2019). "Furthermore, miR‐16‐5p enhances the radiosensitivity of prostate cancer cells by modulating the cyclin D1/E1‐pRb‐E2F1 signaling pathway." (PMID 31505105, 2019). "In this study, an E2F1 ChIP-seq peak file from a prostate cancer cell-line LNCaP was used to evaluate whether using 1 kb, instead of 10 kb, can improve the performance of Cistrome-GO for promoter-dominant TFs." (PMID 31053864, 2019). "Utilizing prostate cancer and bladder cancer cell lines, our data support our hypothesis that E2F1 suppresses SIRT6 transcription and facilities cancer cell glycolysis." (PMID 25816777, 2015). "Also in prostate cancer E2F1 binds the ATAD2 gene regulatory region to activate its gene transcription." (PMID 26308378, 2015).
prostate carcinoma (continued). "The combined effect of cell cycle deregulation via RB1 and E2F1 and of AR re-activation was hypothesized to promote prostate cancer progression to castration resistance." (PMID 25575823, 2015). "Here we tested our hypothesis in bladder and prostate cancer cell lines and found that E2F1 could indeed suppress SIRT6 transcription and promote cancer cell glycolysis." (PMID 25816777, 2015). "Studies in progress will determine the effect of longer durations of treatment with the peptide, mechanisms of resistance and combinations of the peptide with agents used to treat prostate cancer, that include taxotere and DNA damaging agents, given the role of E2F-1 in DNA repair." (PMID 24658650, 2014). "This suggests that the effects of ICAM-1 upregulated by E2F1 knockdown may have important implications for the systemic treatment of prostate cancer." (PMID 24742333, 2014). "The active, hypophosphorylated form of the protein binds transcription factor E2F1 which may induce suppression of apoptosis in prostate cancer." (PMID 22028636, 2011). "To test this hypothesis, we used DU145 prostate cancer cell lines stably expressing Flag-E2F1 WT or Flag-E2F1 K117R mutant in SETD6 WT and SETD6 KO context that have been described in our previous study and were characterized with respect to the expression of SETD6 and the different forms of E2F1." (PMID 41540805, 2026). "Moreover, the human nucleoporins POM121 and importinβ mediate the nuclear import of a series of oncogenic transcription factors (e.g., such as the transcription factor E2F1 (E2F1), transcription factor p64 (c-Myc), and androgen receptor (AR), promoting the progression of prostate cancer (PCa)." (PMID 39080077, 2024). "Moreover, since AR and E2F1 share binding sites in prostate cancer cells and their co-occupancy is dependent on AR, a similar interaction between GR and E2F1 could occur in NEPC." (PMID 39027480, 2024). "Finally, we overexpressed E2F1 and observed its promotion of prostate cancer cell proliferation." (PMID 38374143, 2024). "Additionally, we discovered that quinidine could reduce the expression of E2F1 in prostate cancer, providing theoretical support for the combination of quinidine and 8-Br-cGMP in clinical applications." (PMID 38374143, 2024). "Moreover, overexpression of E2F1 has been reported to be related to tumor growth and cell survival in prostate cancer (PCa), whereas knockdown treatment of E2F1 inhibited cell cycle progression, invasion, and migration of PCa cell lines in vitro, as well as tumor growth and EMT in vivo." (PMID 37128280, 2023). "In addition, DEPDC1 could interact with E2F1 and promote its transcriptional activity in prostate cancer, resulting in the activation of the E2F signaling pathway to regulate the G1/S phase cell cycle transition and then increase cell proliferation." (PMID 36768316, 2023). "Interestingly, a study of TFDP3 in prostate cancer emphasized that TFDP3 was coexpressed with E2F1." (PMID 34745961, 2021). "Moreover, avasimibe may attenuate EMT and trigger cell cycle arrest via the E2F-1 signalling pathway in prostate cancer." (PMID 34461908, 2021). "Thus, as an increase in E2F1 expression plays an important role in advanced prostate cancer, the growth inhibition from the DTX+ENZ combined treatment could be caused by the suppression of E2F1 activity." (PMID 32354165, 2020). "Thus, it is important to investigate the role of AR3 and E2F1 in drug-resistant prostate cancers." (PMID 32354165, 2020). "Indeed, over-expressing of E2F1, but not its DNA binding deficient mutant, significantly enhanced glucose uptake and lactate production in bladder and prostate cancer cell lines." (PMID 25816777, 2015). "However, it is still unclear that the roles and mechanisms of E2F1 on prostate cancers." (PMID 24742333, 2014).
prostate carcinoma (continued). "A closer examination of E2F1 expression using tissue microarray found that E2F1 was low in benign and localized prostate cancer, modestly elevated in metastatic lymph nodes from hormone-naive patients, and significantly elevated in metastatic tissues from hormone-resistant prostate cancer patients." (PMID 21106062, 2010). "To demonstrate the SETD6-dependent binding of BRD4 and E2F1 in cells, we performed a GFP-trap assay in DU145 prostate cancer cells." (PMID 41540805, 2026). "The histone lysine demethylase KDM4A serves as a coactivator for E2F1, binding to the promoters of PDK1 and PDK3, thus influencing the metabolic transition between glycolysis and mitochondrial oxidation in prostate cancer." (PMID 41158756, 2026). "In agreement with this, active E2F1/BRD4 transcriptional programs have been identified in prostate cancer cells and cellular data have documented direct effects of BET proteins on E2F1 transcriptional activities." (PMID 41540805, 2026). "Our findings revealed that silencing the NCAPH gene effectively suppressed proliferation, reduced cell cycle progression in prostate cancer cells by directly inhibiting the PI3K/AKT/mTOR pathway, and decreased the expression of the transcription factor E2F1." (PMID 39991770, 2025). "In prostate cancer, GAS5 facilitated the transcription of P27Kip1 by recruiting E2F1 to its promoter, repressing cell proliferation and growth." (PMID 39119602, 2024). "In mouse prostate cancer xenografts, POM121 drives tumor progression through importin-β-dependent nuclear import of androgen receptor, E2F1 and MYC, whereas importin-β inhibitor importazol attenuated tumor growth." (PMID 38177114, 2024). "E2F1 inhibited the binding of NF-κB p65 to the ICAM-1 promoter and eliminated the antitumor immune effect of ICAM-1 against prostate cancer cells." (PMID 38187112, 2023). "E2F1 and E2F2 are upregulated in several cancer types, including prostate cancer (PCa), in which overexpression of these E2Fs correlates with poor clinical outcome." (PMID 36230876, 2022). "Overall, E2F1, E2F2, E2F3, and E2F5 were found to be correlated with the malignant progression of prostate cancer." (PMID 35531101, 2022). "Altogether, these results indicate that E2F1 and E2F2 play a critical role in preserving genome integrity during S-phase in prostate cancer cells." (PMID 36230876, 2022). "Our results showed that the expression of E2F1–3, E2F5, and E2F6 was higher in prostate cancer tissues than in benign tissues." (PMID 35531101, 2022). "In summary, E2F1, E2F2, E2F3, E2F5, and E2F6 were found to be correlated with the malignant progression of prostate cancer." (PMID 35531101, 2022). "These are well established oncogenic pathways in prostate cancer, driven by transcription factors AR, MYC and E2F1/2." (PMID 35406480, 2022). "In our previous study, we found that E2F1 promoted the invasion and migration of prostate cancer cells by regulating CD147 and, importantly, that overexpression of E2F1 predicted a poor prognosis of human PCa." (PMID 35531101, 2022). "Instead, E2F1/E2F2 hinder premature CDK1 activation during S phase, which is key to ensure genome stability and viability of prostate cancer cells." (PMID 36230876, 2022). "Subsequently, we further investigated the alteration of immune cell components in samples with altered expressions of E2F1, E2F2, E2F3, E2F5, and E2F6 in prostate cancer based on TCGA." (PMID 35531101, 2022). "Additionally, E2F1 may be involved in the transformation of lethal prostate cancer." (PMID 35531101, 2022). "FOXM1 and E2F1, which have been shown to transcriptionally regulate RRM2 expression in prostate cancer, glioblastomas, and CRC, respectively, were also included." (PMID 34234118, 2021).